MAL (mal, T cell differentiation protein (MAL blood group))
Diseases named in the same sentence as MAL in open-access papers (continued):
Sharing a sentence is not in itself a finding about the gene and the disease.
squamous cell carcinoma (3 papers, 2021 to 2022). A carcinoma arising from squamous epithelial cells. "MAL expression is gradually lost during progression from pre-invasive lesions to squamous cell carcinoma in tobacco-associated oral cancer." (PMID 33946345, 2021). "Silencing of MAL via its promoter methylation contributes to the transformation and oncogenesis of HPV-infected cervical cells, suggesting MAL methylation as a diagnostic biomarker for squamous cell carcinoma (SCC) and adenocarcinoma (AdCA), as well as their precancerous lesions." (PMID 35402283, 2022). "MAL hypermethylation is, therefore, a common event in human esophageal adenocarcinoma but uncommon in squamous cell carcinoma." (PMID 33946345, 2021). "Regarding tumor histology, 86.4% of the 19 squamous cell carcinomas were positive for CADM1 and /or MAL." (PMID 36010947, 2022).
acute megakaryocytic leukemia (2 papers, 2021 to 2023). "With LIM kinase upregulation, MAL (megakaryocytic acute leukemia) can no longer be sequestered by actin monomers and translocates to the nucleus, where it activates SRF (serum response factor), a factor that responds to morphological changes in the actin cytoskeleton." (PMID 36901722, 2023).
atherosclerosis (2 papers, 2020 to 2021). A disease characterized by the build-up of fatty material and calcium deposition in the arterial wall resulting in partial or complete occlusion of the arterial lumen. "Taken together, our observed findings suggest that the involvement of core genes related to the risk of atherosclerosis might be a critical metric in ubiquitin-mediated proteolysis, Toll-like receptor, and MyD88: MAL (TIRAP) cascades and a beneficial tool for diagnosis and targeted therapy." (PMID 32760426, 2020). "In the context of atherosclerosis, hematopoietic deletion of TRAM or TRIF, instead of MAL, was shown to reduce the influx of aortic macrophages as well as the severity of atherosclerosis in an animal model." (PMID 34499622, 2021).
bladder tumor (2 papers, 2020 to 2022). "In our previous study, we examined both bladder tumor tissues and benign bladder biopsies and found that methylation of both MAL and GHSR was higher in bladder tumor tissues, which underlines the diagnostic utility of these markers." (PMID 32252299, 2020). "It is expected that bladder tumours have a higher tumour load at primary diagnosis than during surveillance, resulting in a higher sensitivity of the marker panel GHSR/MAL in primary tumours." (PMID 35123558, 2022).
colon carcinoma (2 papers, 2008 to 2020). "Two overlapping fragments of the MAL promoter were bisulphite sequenced in 20 colon cancer cell lines." (PMID 18346269, 2008). "From direct bisulphite sequencing of colon cancer cell lines, we have now shown that the DNA methylation of MAL is unequally distributed within the CpG island of its promoter." (PMID 18346269, 2008). "Furthermore, the gene expression of MAL was up-regulated in colon cancer cell lines after promoter demethylation induced by the combined treatment 5-aza-2'-deoxycytidine and trichostatin A." (PMID 18346269, 2008).
colorectal adenoma (2 papers, 2008 to 2015). An adenoma that arises from the colon or rectum. "Using methylation-specific polymerase chain reaction (MSP) the promoter methylation status of MAL was analyzed in 218 samples, including normal mucosa (n = 44), colorectal adenomas (n = 63), carcinomas (n = 65), and various cancer cell lines (n = 46)." (PMID 18346269, 2008).
colorectal tumors (2 papers, 2008 to 2021). "MAL promoter methylation and reduced MAL protein expression are suggested to be of diagnostic value for incipient colorectal tumors." (PMID 33946345, 2021). "The aim of the present study was to investigate the potential of the MAL (T-cell differentiation protein) gene as an early epigenetic diagnostic marker for colorectal tumors." (PMID 18346269, 2008). "Hence, it needs to be established whether MAL promoter hypermethylation is a cause or a consequence of the observed loss of gene expression in colorectal tumors." (PMID 18346269, 2008). "Promoter hypermethylation of MAL was present in the vast majority of benign and malignant colorectal tumors, and only rarely in normal mucosa, which makes it suitable as a diagnostic marker for early colorectal tumorigenesis." (PMID 18346269, 2008). "Among these was the MAL (T-cell differentiation protein) gene, and we then communicated that the CpG rich promoter of MAL seemed to be hypermethylated in the majority of colorectal tumours." (PMID 18346269, 2008).
esophageal neoplasms (2 papers, 2017 to 2023). "Although MAL expression is not prognostic in ESCA, loss of MAL protein expression was detected in incipient esophageal neoplasms in rat models and also in mild esophageal dysplasia in humans." (PMID 37345137, 2023).
fucosidosis (2 papers, 2015 to 2023). "A detailed examination of OL status in a canine model of fucosidosis identified significant OL loss in the corpus callosum and cerebellar white matter, which stabilized by 16 weeks of age, as visualized by decreased CNP, MAG, MAL and PLP1 expression, and reduced CNP and increased CASP6 staining." (PMID 37183607, 2023).
lung carcinoma (2 papers, 2020 to 2023). "Other stronger correlations were that of MAL (LUAD) and MYADM (LUSC) in lung cancer, which was the second most highly ranked in the 2020 ranking, with 12.5% of the new cancer cases, and that of MAL2 and MALL in PAAD, which was ranked twelfth, with 2.7% of the new cases." (PMID 37345137, 2023). "The results showed that the Siaα2-3Galβ1-4Glc(NAc)/Glc binder MAL-II, the Galβ-1,4GlcNAc (type II), the Galβ1-3GlcNAc (type I) binders RCA120 and ECA, as well as the High-Mannose binders HHL, exhibited significantly decreased NFIs in all patients with lung cancer compared with BPD (all p < 0.001)." (PMID 33520694, 2020).
mediastinal tumors (2 papers, 2021 to 2023). "IHC analysis confirmed the selectivity of MAL expression, revealing that approximately 64% of primary mediastinal tumors express MAL." (PMID 37345137, 2023). "Immunohistochemical analysis confirmed the selectivity of MAL expression, revealing that approximately 64% of primary mediastinal tumors express MAL." (PMID 33946345, 2021).
melanoma (2 papers, 2020 to 2021). A malignant, usually aggressive tumor composed of atypical, neoplastic melanocytes. "We also performed correlation analysis between the gene expression of MAL and that of other genes in melanoma." (PMID 33672337, 2021).
oral squamous cell carcinoma (2 papers, 2020 to 2024). "A very recent study, confirmed the presence of AC103563.8 as antisense of MAL in oral squamous cell carcinoma (OSCC)." (PMID 38461243, 2024).
T cell lymphoma (2 papers, 2016 to 2021). "Conversely, other reports have shown MAL overexpression that was associated with T cell lymphoma resistance to therapy." (PMID 26992238, 2016). "Of the T-cell neoplasms, MAL was highly expressed in lymphoblastic tumors, whereas mature T-cell lymphomas were essentially MAL-negative." (PMID 33946345, 2021).
viral infection (2 papers, 2017 to 2020). "However, no involvement of MAL in viral infections has been reported so far." (PMID 31748392, 2020).
allergic reactions (1 paper, 2020). "Also, CALCA and MAL were reported to be highly expressed in the allergic reactions of MTIs." (PMID 33221769, 2020).
asthma (1 paper, 2016). "Our study suggests that a high fat load increases MAL gene expression in asthma, a gene which could be modifying T-cell signal transduction, thereby inducing airway inflammation." (PMID 26751474, 2016). "qPCR confirmed that S100P, S100A16, MAL and MUC1 were significantly increased in the asthma group post-meal." (PMID 26751474, 2016). "Confirming the microarray analysis, we determined that S100P, S100A16, MAL and MUC1 were significantly increased in the asthma group at 4 h post-meal compared with baseline." (PMID 26751474, 2016).
Cerebral ischemia (1 paper, 2022). Restriction of arterial blood supply to the brain associated with insufficient oxygenation to support the metabolic requirements of the tissue. "Interestingly, a positive modulation of the MAL gene expression was also found in studies of our team using C-PC and PCB in animal models of MS and cerebral ischemia, respectively." (PMID 36405721, 2022).
colon adenocarcinoma (1 paper, 2021). "A cluster of 13 CpG loci (11 genes) were identified that displayed differential methylation in colon adenocarcinoma (COAD) (N = 289) compared to normal colon tissues (N = 38): ZNF671, TWIST1 (two CpG loci), TMEFF2, TM6SF1, GAS7, MAL, HIN1 (two CpG loci; SCGB3A1), COL6A2, AKR1B1, GPX7, ARHGEF7)." (PMID 34903270, 2021).
congenital toxoplasmosis (1 paper, 2017). Toxoplasma infection that is present from birth. "Our sequential analysis of other candidate susceptibility loci presented herein, found that TREX1, TIRAP MAL, FOXQ, and TLR9 also had allelic variants significantly associated with susceptibility to congenital toxoplasmosis in the NCCCTS (p < 0.05)." (PMID 28904337, 2017).
cyst (1 paper, 2021). A sac-like closed membranous structure that may be empty or contain fluid or amorphous material. "Mice overexpressing MAL develop multiple large renal cysts, with a close correlation between MAL expression levels and cyst development, the affected tubular segments expressing the highest levels of MAL." (PMID 33946345, 2021).
Down syndrome (1 paper, 2015). "Extending our data on DYRK1A, actin and MAL/SRF, publicly available array data of human Down syndrome patient brain tissue demonstrate a reduced expression of numerous MKL1/SRF target genes." (PMID 26310823, 2015).
endometrioid adenocarcinoma (1 paper, 2020). An adenocarcinoma characterized by the presence of malignant glandular epithelial cells resembling endometrial cells. "In addition, MAL and ASPM had higher expression levels in EC tissues of different subtypes, such as serous carcinoma, endometrioid adenocarcinoma and mixed serous and endometrioid adenocarcinoma." (PMID 32099532, 2020).
enterocolitis (1 paper, 2025). An inflammatory process affecting the small intestine and colon. "In contrast, goats, which share an identical MAL protein sequence with sheep MAL, mainly develop enterocolitis." (PMID 39852980, 2025).
esophageal adenocarcinoma (1 paper, 2021). A malignant tumor with glandular differentiation arising predominantly from Barrett mucosa in the lower third of the esophagus. "In another study, MAL methylation frequency and methylation levels were found to be significantly higher in Barrett’s esophagus, dysplastic Barrett’s esophagus, and esophageal adenocarcinoma than in esophageal squamous cell carcinoma and normal esophagus." (PMID 33946345, 2021).
gastric tumor (1 paper, 2022). "We speculated that abnormal MAL expression may be an important cause of GC; MAL overexpression inhibited the invasion and migration of gastric tumor cells, and this process is regulated by the suppression of STAT3 phosphorylation." (PMID 35093120, 2022). "In this study, we assessed the MAL expression pattern in pericancerous and primary gastric tumor samples." (PMID 35093120, 2022).
leukodystrophies (1 paper, 2022). "We present a missense variant in MAL as the likely cause of hypomyelinating leukodystrophy, resulting in ER mislocalization of mutant MAL leading to possible defects in PLP1 trafficking." (PMID 35217805, 2022). "Here, we report the identification and characterisation of a missense variant in MAL as causative for a rare, hypomyelinating leukodystrophy." (PMID 35217805, 2022). "We report a missense variant p.(Ala109Asp) in MAL as causative for a rare, hypomyelinating leukodystrophy similar to Pelizaeus-Merzbacher disease." (PMID 35217805, 2022). "Our work supports a disease mechanism for leukodystrophies by which mislocalisation of MAL affects the distribution of PLP1, resulting in a hypomyelination disorder similar to Pelizaeus-Merzbacher disease." (PMID 35217805, 2022). "Our results suggest that mislocalisation of MAL affects PLP1 distribution, consistent with known pathomechanisms for hypomyelinating leukodystrophies." (PMID 35217805, 2022).
mucinous carcinomas (1 paper, 2018). "There are six genes (MAL, MYOD1, OSMR, SEPTIN9, SFRP1, and SFRP4) for which hypermethylation is observed almost exclusively or preferentially in mucinous carcinomas." (PMID 29882921, 2018).
Nephroblastoma (1 paper, 2022). An embryonal neoplasm characterized by the presence of epithelial, mesenchymal, and blastema components. "MAL had been reported to play an important role in a variety of tumors, but the role of MAL gene in nephroblastoma had not been reported yet." (PMID 35023304, 2022).
nephronophthisis (1 paper, 2010). Progressive tubulointerstitial injury, inherited in an autosomal recessive pattern, caused by mutations in genes involved in ciliary function, which may result in an end stage renal failure. "Although MAL is located at chromosome 2q13, a region that is involved in large homozygous deletions in juvenile nephronophthisis, no deletions or mutations have been reported yet with respect to human cancer." (PMID 21092172, 2010).
oligodendroglioma (1 paper, 2020). A well-differentiated (WHO grade II), diffusely infiltrating neuroglial tumor, typically located in the cerebral hemispheres. "We used a short hairpin RNA to produce a stable MAL-silenced human oligodendroglioma (HOG) cell line and demonstrated a functional role of MAL in HSV-1 spread." (PMID 31748392, 2020).
oncocytoma (1 paper, 2017). "The chRCC and oncocytoma samples displayed almost identical gene expression profiles for MAL, TMEM255A, RHCG, ATP6V0A4, STAP1, and DEFB1, as demonstrated by both RNA microarray and RNA sequencing, which is in agreement with the known fact that chRCC and oncocytoma are related neoplasms." (PMID 29208006, 2017).
Pelizaeus-Merzbacher disease (1 paper, 2022). "Our results suggest that mislocalisation of MAL affects the distribution of PLP1, consistent with known pathomechanisms for Pelizaeus-Merzbacher disease." (PMID 35217805, 2022).
penile squamous cell carcinoma (1 paper, 2025). "In HPV-related penile squamous cell carcinoma (PSCC), regulatory T cells secrete exosomes containing lncRNAs that interact with miR-619-3p, which leads to increased expression of MAL (Myelin and Lymphocyte protein) in cytotoxic T cells that results in their apoptosis." (PMID 41154440, 2025).
peripheral nerve injury (1 paper, 2021). Injury to a peripheral nerve. "We next further explored the role of the regulation of MAL and NLRP3 targeted by miR-331-3p in repair of peripheral nerve injury." (PMID 34150749, 2021).
rectal cancer (1 paper, 2016). A primary or metastatic malignant neoplasm that affects the rectum. "Ten of the 36 (EYA4, FOXI2, CNRIP1, SFRP1, ADHFE1, C2orf40, MAL, PHACTR3, SST, TMEFF2) were known as rectal cancer related genes with aberrant methylation." (PMID 27566576, 2016).
Renal cyst (1 paper, 2021). A fluid filled sac in the kidney. "Since MAL overexpression produces dilated apical surfaces in MDCK cells, it is plausible that that the effect of MAL overexpression on the formation of multiple lumens in MDCK cells or of renal cysts in mice arises from the production of a large excess of apical membrane." (PMID 33946345, 2021).
rheumatoid arthritis (1 paper, 2012). A chronic, systemic autoimmune disorder characterized by inflammation in the synovial membranes and articular surfaces. "TLRs also promote the inflammatory and destructive processes in rheumatoid arthritis with adapters MyD88 and MAL/TIRAP having a significant role." (PMID 23305364, 2012).
tumor (59 papers, 2004 to 2026). "For example, upregulation of genes (e.g. CHI3L1, S100A7, and MAL) is associated with poor prognosis, increases aggressiveness, and tumor microenvironment modulation." (PMID 40802546, 2025). "Another tumor suppressor gene with reduced expression during cervical carcinogenesis is T-lymphocyte maturation-associated protein (MAL), which is associated with apical transport of membrane proteins." (PMID 37047452, 2023). "Gain- and loss-of-function assays showed that MAL is a tumor suppressor; it inhibits the proliferation, invasion, and EMT in cancer cells." (PMID 38069262, 2023). "Gain- and loss-of function assays showed that interference with MAL significantly increased tumor cell proliferation, metastasis, invasion and the EMT." (PMID 35093120, 2022). "MAL serves as a prognostic factor and closely associates with tumor microenvironment in WT." (PMID 35023304, 2022). "As promoter hypermethylation of MAL could already be detected in cancer precursor lesions, it has been suggested as a tumour-suppressor gene with diagnostic value." (PMID 19002170, 2008). "Myelin and lymphocyte myelin (MAL) protein has been suggested as a prognostic biomarker due to its implications in the interaction between the tumor and its microenvironment." (PMID 40142302, 2025). "It is of note that the level of expression of MAL in the tumor cells was correlated with clinical data concerning time of remission, whereby MAL-positive tumors responded to the treatment significantly more slowly than did the MAL-negative tumors." (PMID 37345137, 2023). "MAL was expressed at high levels in normal gastric samples and very low levels in the primary tumor and corresponding metastases." (PMID 35093120, 2022). "In this study, we tried to clarify the relationship between MAL expression and the prognosis of WT through related bioinformatics methods, and at the same time explored its relationship with tumor microenvironment and related signaling pathways." (PMID 35023304, 2022). "The most frequently tested host-genome methylation markers in cervical smears and tumours are cell adhesion molecule 1 (CADM1) and T-lymphocyte maturation-associated protein (MAL)." (PMID 35725812, 2022). "In the present study, MAL expression in tissues from patients with GC was low; more importantly, its expression was negatively correlated with the tumor stage of the patient." (PMID 35093120, 2022). "It will be highly worthwhile to determine how the absence of MAL expression affects cellular membranes in order to understand the tumor suppressor role of MAL and the mechanism by which MAL silencing modifies the cell to facilitate cancer progression." (PMID 33946345, 2021). "Keeping in mind our model of MAL function as machinery for organizing condensed membrane environments, we propose that the MAL is a tumor suppressor in many types of cancer." (PMID 33946345, 2021). "This suggests a tumor suppressor role for MAL, which was demonstrated by increased tumor cell apoptosis after ectopic expression; suppression of motility and invasion were also noted." (PMID 26992238, 2016). "The tumor suppressor Eplin-α is thus a novel cytoskeletal target gene regulated by the actin-MAL-SRF pathway." (PMID 20236507, 2010). "The tumor suppressor Eplin-α is thus a novel cytoskeletal target gene transcriptionally regulated by the actin-MAL-SRF pathway, which supports a role in cancer biology." (PMID 20236507, 2010). "When optimized cut-off values were selected, the single expression level of IL1RN, MAL or MMP1 correctly predicted the tumor or normal nature of tissue samples in, respectively, 87, 86 and 88 cases out of the 92 tested samples." (PMID 19835631, 2009). "The association between promoter methylation and reduced mRNA expression strengthens the biological relevance of MAL methylation and supports a putative role as tumour-suppressor gene." (PMID 19002170, 2008).